ERG (ETS transcription factor ERG)
Diseases named in the same sentence as ERG in open-access papers (continued):
Sharing a sentence is not in itself a finding about the gene and the disease.
prostate carcinoma (continued). "The potential utility of the TMPRSS2:ERG fusion product as an independent prognostic marker for patients with clinically localised prostate cancer remains controversial." (PMID 17971772, 2007). "This is the first documented case suggesting a potential link between COVID-19-related prostatitis and subsequent prostate cancer in a TMPRSS2::ERG-altered patient without hereditary predisposition." (PMID 41267989, 2025). "BAP1 interacts indirectly with ERG, a key oncogene in prostate cancer." (PMID 40136571, 2025). "Notably, the TMPRSS2-ERG fusion, which is present in approximately 50% of prostate cancers, leads to an AR-mediated upregulation of ERG signaling and is implicated in pathways that lead to metastasis rather than cell growth." (PMID 40075623, 2025). "Moreover, the aberrant expression of ERG resulting from the TMPRSS2-ERG fusion is closely associated with increased cell proliferation, neovascularization, and invasive behavior in prostate cancer." (PMID 39963114, 2025). "Oncogenic TMPRSS2:ERG (ERG+) gene fusions are seen in approximately 50% of prostate cancers." (PMID 40005682, 2025). "Many prostate cancers carry a translocation leading to the TMPRSS2::ERG oncoprotein leading to amplified ERG levels which could potentially be detected by FLI1 1.2." (PMID 41283512, 2025). "This rearrangement results in ERG overexpression, which contributes to prostate cancer development." (PMID 41374944, 2025). "It has been postulated that the short distance between the TMPRSS2 and ERG genes on the chromosome 21 could account for the higher frequency of TMPRSS2:ERG fusions in prostate cancer." (PMID 40332527, 2025). "TMPRSS2::ERG, the hallmark fusion of prostate cancer, failed to be reported by both LongGF and FusionSeeker, while CTAT-LR-Fusion detects 45, 98, and 104 long isoform reads supporting TMPRSS2::ERG across the three sequenced libraries." (PMID 40086881, 2025). "Most of these genes are prostate cancer-related genes (i.e., ERG, PCA3, and AR-V7)." (PMID 39859516, 2025). "This is the first reported case suggesting a potential association between COVID-19-related prostatitis, TMPRSS2::ERG fusion, and prostate cancer development in the absence of hereditary predisposition." (PMID 41267989, 2025). "Loss of MAP3K7 was linked to early PSA recurrence in prostate cancer and was commonly associated with the absence of ERG-TMPRSS2 fusion." (PMID 39796635, 2024). "The data presented here supports an important and vital role for LAMTOR4 as a biomarker associated with prostate cancer progression and metastasis and with significant clinical outcome prognostic value as an individual biomarker or in association with PTEN loss/ERG expression." (PMID 39125671, 2024). "Overexpression of ERG may also follow fusion with other genes including SLC45A3, FOXP1, and HERV-K, among others however, this is seen in only about 10% of cases of prostate cancer with ERG overexpression." (PMID 38730435, 2024). "The metabolomic characteristics of prostate cancer include heightened Fatty Acid Synthase (FAS)-mediated fatty acid metabolism and uptake, particularly in Transmembrane Protease, Serine 2 (TMPRSS2)-Ets variant 1 (ERG) translocation-positive samples." (PMID 38791108, 2024). "Anti-ERG was developed as an immunohistochemistry stain for prostate cancer in 2011." (PMID 38933637, 2024). "ERG expression is independently associated with increased FASN expression, as well as increased expression of other fatty acid metabolic genes, in prostate cancer." (PMID 38112617, 2024). "ERG fusion proteins have been shown to promote prostate cancer cell proliferation and invasion." (PMID 38256434, 2024). "The existence of TMPRSS2:ERG in prostate cancer, along with the significant modulation of TMPRSS2 by androgens, has led to the speculation that the male predominance in the COVID-19 pandemic may be partly attributed to TMPRSS2." (PMID 38793660, 2024).
prostate carcinoma (continued). "The co-occurrence of CHD1 deletion and SPOP mutation in ERG fusion–negative prostate cancer has been described previously, but progression modeling reveals these as early, codriving events." (PMID 39347576, 2024). "These Oligo-DbTACs were delivered into PC-3 prostate cancer cells, which overexpressed ERG." (PMID 37495569, 2023). "Finally, ERG has been identified as being consistently overexpressed in malignant epithelial cells in prostate cancer and has also been shown to be involved in proliferation, as well as vasculo- and angiogenesis." (PMID 37762215, 2023). "Thus, about half of all cases of prostate cancer have a fused TMPRSS2-ERG transcript, which is formed due to an intrachromosomal rearrangement leading to the fusion of two genes: TMPRSS2 and ERG." (PMID 37298233, 2023). "In the present study, we aimed to observe the patterns of ERG immunoexpression and PTEN immunohistochemical loss in prostate cancer precursor lesions (HGPIN), invasive prostate carcinoma, as well as in IDCP in correlation with the immunohistochemical expression in the adjacent invasive carcinoma." (PMID 37185705, 2023). "In recent years, TMPRSS2:ERG has been a major focus of research in the field of prostate cancer." (PMID 36980776, 2023). "Due to its high frequency in prostate cancer cases, the TMPRSS2:ERG fusion might be more promising as a diagnostic marker rather than as prognostic." (PMID 37511059, 2023). "Our findings in ERG-mediated prostate cancer cells suggest that this approach may have a general role in ERG-driven malignancies." (PMID 37735473, 2023). "Also, it is obtained that most of the studied genes (TMPRSS2, ERG, ETV5 and AR) are associated with pathways involved in the development of prostate cancer." (PMID 37287057, 2023). "The ERG rearrangements are reported in 23 of 29 prostate cancer samples." (PMID 37310937, 2023). "More specifically, when ERG was negative in prostate carcinoma, PTEN displayed a heterogeneous loss (score 1)." (PMID 37185705, 2023). "The miRNAs overexpression was induced in prostate cancer cells (VCaP) to analyze ERG expression." (PMID 37310937, 2023). "VCaP prostate cancer cells express ERG due to a TMRPSS2/ERG rearrangement." (PMID 37956771, 2023). "In addition, the oncogenic activation of ERG through this gene fusion has been detected in 60% and 30% of prostate cancer in CA and AA men respectively." (PMID 36768533, 2023). "The TMPRSS2:ERG gene fusion, which is recognized as one of the most common gene fusions found in prostate cancer patients, was identified in 15 of 44 patients (34%), slightly lower than a previously reported estimate of 42.6% in metastatic castrate resistant-prostate cancers." (PMID 38050021, 2023). "The mechanism responsible for ERG-mediated prostate cancer are not well understood." (PMID 37973913, 2023). "Notably, a substantial proportion of prostate cancers, up to 74%, can be attributed to fusions found in ETS-family genes (ERG, ETV1, ETV4, and FLI1) or mutations in genes such as SPOP, FOXA1, or IDH1." (PMID 38067216, 2023). "That the prognostic role of PSAP was particularly strong in ERG-negative but was less prominent in ERG-positive cancers is in line with various earlier studies describing prognostic molecular features in prostate cancer that were either restricted to ERG-positive or ERG-negative cancers." (PMID 37892063, 2023). "In prostate cancer, ERG overexpression leads to ductal dysplasia, PIN metastasis, and advanced disease which may be related to the role of ERG in promoting angiogenesis." (PMID 37310937, 2023). "TMPRSS2 is also strongly related with other genes involved in prostate cancer, like ERG, ETV5 and AR, whose characterization could help to clearly classifying COVID-19." (PMID 37287057, 2023). "Interestingly, NF-κB activation is elevated in ERG fusion-positive prostate cancer patients and cancer cell lines." (PMID 36899924, 2023).
prostate carcinoma (continued). "We hypothesized that the therapeutic potential of ETS inhibitors targeting EWS-FLI1 (Ewing sarcoma) and ERG-driven tumors (prostate cancer) can be expanded to pediatric leukemia as they are well known to have deregulated ETS activity." (PMID 37895265, 2023). "As predicted, V5-tagged EWS/FLI1 expressed in PC3 prostate cancer cells bound to purified ERG." (PMID 37956771, 2023). "In occurrence with CHD1 deletion, SPOP mutations define a distinct prostate cancer subtype, characterized by genomic instability, increased AR transcriptional activity, absence of ERG rearrangements, and increased DNA methylation." (PMID 36776288, 2023). "ERG gene rearrangements are frequently observed in prostate cancer." (PMID 37373115, 2023). "Ets-related gene (ERG) is overexpressed as a fusion protein in prostate cancer." (PMID 37310937, 2023). "Therefore, ERG and AR overexpression result in prostate cancer cells having increased tolerance to androgen receptor antagonists." (PMID 35563163, 2022). "Indeed, our previous study shows that ERRα and ERG can regulate each other in a synergistic manner and form a reciprocal regulatory loop to advance the progression of prostate cancer." (PMID 35526071, 2022). "In addition to its role in development and in the vascular and hematopoietic systems, ERG plays a central role in prostate cancer." (PMID 35267426, 2022). "For example, previous studies have reported the detection of fusion between TMPRSS2 and ERG in prostate cancer tissues, and high expression of PSMA in advanced PC or mCRPC tissues which is related to related to higher tumor stage/Gleason score/preoperative PSA levels." (PMID 35402423, 2022). "Low levels of ERG expression were also seen in prostate cancers from men in Ghana and Senegal." (PMID 35104804, 2022). "In prostate cancer, ERG often forms a fusion gene with transmembrane protease, serine 2 (TMPRSS2)." (PMID 35954308, 2022). "ERG binds to αβ-tubulin, and when overexpressed, reduces binding site availability for taxane-induced microtubule polymerization, leading to taxane resistance in prostate cancer cells and tumors." (PMID 35884386, 2022). "These rearrangements have a significant influence on ERG expression level, which could provide clues for targeted therapy of prostate cancer patients." (PMID 36579559, 2022). "ETS-related gene (ERG) fusion affects prostate cancer depending on the degree of expression of ERG." (PMID 36579559, 2022). "In around 6% of ERG rearranged prostate cancers, SLCA45A3 represents the 5′ fusion partner of ERG." (PMID 36337169, 2022). "Previous data suggested that ERG fusions are detected in areas of high-grade prostatic intraepithelial neoplasia and likely represent an early event that precedes other chromosome-level alterations found in prostate cancer." (PMID 35050902, 2022). "Interestingly, we found high expression of antioxidant genes; SOD1, TXN, LAMTOR5, and ATOX1 in prostate cancer patients having higher ERG fusion expression." (PMID 35508713, 2022). "Among the ETS members, ERG (ETS-related gene) plays important roles in normal physiology and tumorigenesis, with its overexpression detected in several tumor types, including Ewing’s sarcoma, hematological malignancies and prostate cancer (PCa)." (PMID 35267426, 2022). "Moreover, inhibition of the enzymatic activity of these proteins hampered ERG-mediated transcriptional regulation with a consequent reduction in the capacity of prostate cancer cells overexpressing ERG to invade." (PMID 35267426, 2022). "For example, PXN, which is known as an oncogene in prostate cancer, has higher expression in the ERG and SPOP subtypes of prostate cancer, as compared to normal cells, and lower expression in ETV1 and ETV4 subtypes of prostate cancer, as compared to normal cells." (PMID 36289913, 2022).
prostate carcinoma (continued). "Hence, it remains challenging to faithfully distinguish prostate cancer with ERG rearrangement from those with wild type ERG and other molecular subtypes based only on the microscopic evaluation of H&E-stained pathological tissues." (PMID 35513774, 2022). "Correlation between ERG expression and phospho-p65 was also observed in prostate cancer tissue microarray and expression of mutants mimicking the phosphorylated form promoted invasion and anchorage-independent colony formation of immortalized and tumorigenic prostatic cells." (PMID 35267426, 2022). "In agreement with previous findings, ERG protein was associated with morphological phenotypes associated with poorer prognosis, including reactive stroma, invasive cribriform carcinoma, and IDC‐P, which support that ERG protein is a biomarker for aggressive prostate cancer." (PMID 35574900, 2022). "The association between statin use and prostate cancer did not vary by TMPRSS2:ERG fusion (ERG) status." (PMID 35732821, 2022). "In prostate cancer, the ERG protein also cooperates with the AR to influence disease progression." (PMID 36212399, 2022). "Interestingly, it has been shown in prostate cancer cells that the deubiquitinase USP9X interacts with ERG and promotes its stabilisation to decrease prostate cancer cell proliferation." (PMID 35723257, 2022). "The commercial available assay ExoDx Prostate (IntelliScore) (NCT03235687, NCT03031418, NCT04720599, NCT02702856) is based on the detection of three RNAs (PCA3, SPDEF, ERG) in urinary sEVs from prostate cancer patients by quantitative reverse transcription-polymerase chain reaction (RT-PCR)." (PMID 36242076, 2022). "The most prevalent genetic rearrangement in prostate cancer involves the fusion of the androgen-regulated gene TMPRSS2 with the ETS transcription factor ERG, which is estimated to occur in ~50% of prostate cancer cases being by far the single most common genetic fusion gene in solid tumors." (PMID 33634124, 2021). "Apatient-specific individual risk score is evaluated based on an original algorithm thatcombines the expression level of three RNAs (PCA3 noncoding RNA, ERG mRNA, and SPDEFmRNA), which are correlated with clinically significant prostate cancer, detected directlyin urinary EV RNAs." (PMID 39703905, 2021). "ERG has been found to be required for hematopoiesis, hematopoietic stem-cell function, and the maintenance of normal platelet numbers, and it acts as an oncogene in leukemias, as well as solid tumors, such as prostate cancer." (PMID 33562405, 2021). "In terms of prostate cancer fusion genes, the expression of ERG has been shown to be retained in the PDXs along with other molecular, histopathologic, and genomic characteristics, indicating PDXs to be a valuable strategy to assess fusion-specific therapeutic options in the future." (PMID 33634124, 2021). "The first of them, LINC02418, we found overexpressed in the ERG-positive subtype of prostate cancer and, also, differentially expressed between colorectal cancer (CRC) tissues and noncancerous tissues and upregulated in NSCLC (non-small cell lung cancer) tissues." (PMID 33672425, 2021). "The TMPRSS2–ERG gene fusion and subsequent overexpression of the ERG transcription factor occurs in ∼50% of prostate tumors, making it the most common abnormality of the prostate cancer genome." (PMID 33554122, 2021). "Furthermore, ERG was deubiquitylated by USP9X thus stabilized protein levels in prostate cancer cells." (PMID 34112167, 2021). "Moreover, TMPRSS2 tends to form a fusion with ERG, which is present in 40-80% prostate cancers and promotes cell migration and metastasis of prostate cancer." (PMID 34168096, 2021). "It is hypothesized that the down-expression of 4.1N is correlated with overexpression of oncogenic transcription factor ETS-related gene (ERG) in prostate cancer." (PMID 34589518, 2021).
prostate carcinoma (continued). "Another report revealed that the HGF/ETS pathway could be active in the TCGA molecular subgroup of TMPRSS2/ERG fused prostate cancers (50%)." (PMID 34123781, 2021). "Notably, the most striking changes between the two groups were found again in the AR/ERG co-bound gene set in primary prostate cancers 3,6." (PMID 33531470, 2021). "More recent efforts have revealed several other downstream effectors of ERG in prostate cancer." (PMID 33634124, 2021). "Our data reveals a low rate of ERG fusion in Sardinian prostate cancer." (PMID 33391440, 2021). "oligonucleotide‐based proteolysis‐targeting chimeras (O'PROTACs), which employ unique DNA sequences as natural “ligand” of targeting proteins, are developed to effectively destruct lymphoid enhancer‐binding factor 1 (LEF1) and ETS‐related gene (ERG) and inhibit prostate cancer cell growth." (PMID 34397171, 2021). "Therefore, prostate cancers harboring ERG gene fusions are considered a distinct molecular subtype of prostate cancer." (PMID 34191807, 2021). "To further investigate how ERK phosphorylation regulates ERG-mediated transcription we conducted an immunoprecipitation (IP) coupled with mass spectrometry of total cellular ERG from VCaP prostate cancer cells which express ERG due to a TMPRSS2/ERG gene rearrangement." (PMID 34314419, 2021). "More than 90% of prostate cancer samples that overexpress ERG harbor the TMPRSS2:ERG fusion gene." (PMID 33634124, 2021). "ERG overexpression is now an instrumental indicator in the diagnosis of prostate cancer." (PMID 34630112, 2021). "Interestingly, high expression levels of ERGIC1 are revealed in prostate cancer tissues, and its silencing down-regulates the ERG oncogene." (PMID 34439361, 2021). "Interestingly, an ASO designed to induce the skipping of the out-of-frame exon 4 of the fusion gene ERG was developed to suppress its function in prostate cancer cells and markedly reduced ERG protein levels, resulting in decreased cell proliferation." (PMID 34414317, 2021). "There is a considerable percentage of prostate cancers in which TMPRSS: ERG fusion was detected." (PMID 34204596, 2021). "Therefore, our findings suggest that efforts to inhibit ERG function in prostate cancer should focus on the role of ERG in transcriptional activation, which is required for tumor-promoting activities both in the presence and absence of AKT activation." (PMID 34314419, 2021). "However, ubiquitin-mediated control of ERG has been charted largely in the context of prostate cancer (PCa)." (PMID 34066106, 2021). "In agreement with recent reports, lentiviral-transduced point mutants of SPOP (SPOP-Y87C, SPOP-W131G) or a truncated version of ERG, which typically results from gene fusion with androgen-regulated genes in prostate cancer (ΔERG, amino acids 33–486), promoted cell growth 13–16." (PMID 33531470, 2021). "Moreover, targeting ETV1 and ERG in prostate cancers significantly reduced invasion and metastasis both in vitro and in vivo." (PMID 33918387, 2021). "Likewise, the lnc-SAYSD1-1 also bioinformatically allows to distinguish the ERG-positive from all the other subclasses of prostate cancer with a Gleason score ≤ 3+4." (PMID 33672425, 2021). "That elevated PNUTS expression which was significantly associated with the majority of the analyzed deletions in ERG-negative cancers highlights that elevated PNUTS levels are either a cause or a consequence of genomic instability in prostate cancer cells." (PMID 32377272, 2020).